TAGAP (T cell activation RhoGTPase activating protein)
Description:
May function as a GTPase-activating protein and may play important roles during T-cell activation.
Synonyms: TAGAP1; FKSG15; FLJ32631; IDDM21; ARHGAP47
Tractability: No criterion of Open Targets' tractability assessment is met for any kind of drug.
Gene: Protein-coding gene on chromosome 6 (159,034,481 to 159,095,823, reverse strand). Ensembl gene ENSG00000164691.
Subcellular location (Human Protein Atlas): Cytosol
Pathways (Reactome):
Signal Transduction: CDC42 GTPase cycle; RAC1 GTPase cycle; RHOA GTPase cycle
Gene Ontology:
Molecular function: protein binding; GTPase activator activity
Biological process: regulation of small GTPase mediated signal transduction; regulation of Rho protein signal transduction; signal transduction
Cellular component: cytosol
Genetic constraint (gnomAD): Loss-of-function variants: 17 observed, 35.05 expected, observed/expected ratio (o/e) 0.49, 90% interval 0.33 to 0.73. The upper end of that interval is the gene's LOEUF score, 0.73, which puts it in group 2 of 6, group 1 being the genes least tolerant of losing a copy. Missense variants: 779 observed, 950.1 expected, observed/expected ratio (o/e) 0.82, 90% interval 0.77 to 0.87. Synonymous variants: 366 observed, 391.69 expected, observed/expected ratio (o/e) 0.93, 90% interval 0.86 to 1.02.
Homologues: Orthologues: chimpanzee TAGAP (99% identical), macaque TAGAP (95% identical), dog TAGAP (73% identical), guinea pig TAGAP (72% identical), mouse Tagap (67% identical), rat Tagap (67% identical), pig TAGAP (66% identical), rabbit TAGAP (64% identical), tropical clawed frog tagap (42% identical), mouse Tagap1 (40% identical), zebrafish tagapb (29% identical), zebrafish tagapa (25% identical), and 3 more. Paralogues in human: ARHGAP20 (22% identical).
Diseases named in the same sentence as TAGAP in open-access papers:
TAGAP is named in the same sentence as 31 diseases in open-access papers, as found by Europe PMC text mining. Sharing a sentence is not in itself a finding about the gene and the disease. The quoted sentences say what the papers report.
autoimmune disease (11 papers, 2010 to 2025). A disorder resulting from loss of function or tissue destruction of an organ or multiple organs, arising from humoral or cellular immune responses of the individual to their own tissue constituents. "The TAGAP gene locus has been linked to several infectious diseases or autoimmune diseases, including candidemia and multiple sclerosis." (PMID 32312989, 2020). "T cell activation Rho GTPase-activating protein (TAGAP) contains several SNP which are associated with progression of various autoimmune disease such as psoriasis, RA, Crohn‘s disease, CD, and MS." (PMID 31319592, 2019). "Genetic polymorphisms in TAGAP gene have been associated with many diseases including rheumatoid arthritis, multiple sclerosis and other autoimmune disorders." (PMID 29329296, 2018). "In exploring the overlap between T1D, CeD and RA, there is strong evidence that variation within the TAGAP gene is associated with all three autoimmune diseases." (PMID 20854658, 2010). "This confirms the finding of a previous study showing association of the TAGAP locus with RA but suggests that the variant associated with autoimmune diseases is more strongly associated than that reported previously." (PMID 20854658, 2010). "Interestingly, one of these genes is TAGAP, whose locus has been genetically associated to several infectious and autoimmune diseases, including candidemia, multiple sclerosis and CeD." (PMID 35371081, 2022). "Data from the current study extend that of previous work identifying that CTLA-4, the IL2_21 region, 6q23 (TNFAIP3), SH2B3, PRKCQ, MMEL1 and now TAGAP are susceptibility loci that are common to the three autoimmune diseases examined in the current study: T1D, CeD and RA." (PMID 20854658, 2010). "The TAGAP gene encodes a member of the Rho GTPase-activator protein superfamily involved in T cell activation and co-regulation with IL-2, which has been previously associated with several autoimmune diseases, including rheumatoid arthritis, celiac disease, and multiple sclerosis." (PMID 27015091, 2016). "TBX21 together with TGIF1 are predicted to target TAGAP, that is a known regulator of T cell differentiation and autoimmune diseases." (PMID 39090334, 2024). "As reported, TAGAP is widely involved in some autoimmune diseases and cancer." (PMID 39998561, 2025). "In addition, as the activator of Rho GTPases, TAGAP could exhibit certain effects on autoimmune diseases by overactivation of T cells." (PMID 39998561, 2025). "Many of these genes have either known roles in Treg differentiation, stability and function (CD48, IL6ST, EZR, ELMO1, IL18R1), or altered expression in human Treg in autoimmune disease (SLAMF1, ANKRD55, TAGAP)." (PMID 35773720, 2022). "These traits are clinically related and colocalized at 13 loci, including sites near genes that regulate eosinophil biology (ETS1 and ID2) and autoimmune disease (KIAA1109 and TAGAP)." (PMID 32600345, 2020).
celiac disease (9 papers, 2016 to 2024). An autoimmune genetic disorder with an unknown pattern of inheritance that primarily affects the digestive tract. "We found 54 single-nucleotide polymorphisms (SNPs) in 5 genes associated with celiac disease (TAGAP, IL18R1, RGS21, PLEK, and CCR9) in time to celiac disease analyses (10−4>P>5.8x10−6)." (PMID 27015091, 2016). "On the other hand, association evidence for RGS21, IL18R1, PLEK, CCR9, TAGAP was only found for celiac disease." (PMID 27015091, 2016). "However, confirmatory evidence (p<10−4) was found for SNPs in five regions previously reported to be associated with celiac disease (TAGAP, IL18R1, RGS21, PLEK, and CCR9)." (PMID 27015091, 2016). "Researchers have been studied that IBD and celiac disease have the similar genetic background; IL18RAP, PTPN2, TAGAP, and PUS10 have been identified as shared risk loci for both CD and celiac disease." (PMID 36204317, 2022). "Another study in children was able to evidence the increased risk (>90%) of developing celiac disease by the genotype of five candidate genes (SH2B3, RGS1, TAGAP, cREL, and LPP)." (PMID 32365683, 2020). "Study on T1D risk locus and celiac disease has been done on a large number of patients, evidence was found that the T-cell activation RhoGTPase activating protein (TAGAP) locus, which are strongly related with celiac disease but has a protective effect on T1D." (PMID 32815547, 2020).
rheumatoid arthritis (7 papers, 2012 to 2025). A chronic, systemic autoimmune disorder characterized by inflammation in the synovial membranes and articular surfaces. "Upregulation of CALR, PRDM1, STAT1, TAGAP and TNRC6B has been associated elsewhere with adult rheumatoid arthritis or juvenile polyarticular arthritis." (PMID 24000795, 2013). "In rheumatoid arthritis, overexpressed TAGAP could disrupt the balance between Th17 and regulatory T (Treg) cells transformation, promoting Th17 cell differentiation, releasing more inflammatory factors, and exacerbating the progression of rheumatoid arthritis." (PMID 39998561, 2025). "For example, rs3184504, a nonsynonymous SNP in SH2B3 that was associated in GWAS with BP, coronary heart disease, hypothyroidism, rheumatoid arthritis, and type 1 diabetes, is a trans-eQTL for 6 of our 34 BP signature genes from the meta-analysis (FOS, MYADM, PP1R15A, TAGAP, S100A10, and FGBP2)." (PMID 25785607, 2015). "CD, type I diabetes (T1D), and rheumatoid arthritis (RA) share the HLA region, and other non-HLA regions, including IL2-IL21, SH2B3, and TAGAP regions." (PMID 23008734, 2012).
multiple sclerosis (5 papers, 2016 to 2022). A progressive autoimmune disorder affecting the central nervous system resulting in demyelination. "Our previous study finds that TAGAP plays a critical role in the antifungal innate immune response, and regulates peripheral T helper cells differentiation, which partially clarify the mechanism of TAGAP polymorphism to multiple sclerosis susceptibility." (PMID 36704549, 2022). "Similarly, in experimental autoimmune encephalomyelitis model of multiple sclerosis, TAGAP deficient mice develop significantly attenuated disease." (PMID 32312989, 2020). "Individuals who carry multiple sclerosis (MS)-associated TAGAP polymorphism show deregulated Th17 and Th1 cell abundance in the peripheral blood mononuclear cells (PBMCs), which partially explain the mechanism of TAGAP polymorphism to multiple sclerosis (MS) susceptibility." (PMID 36704549, 2022).
Candidemia (4 papers, 2016 to 2022). A form of invasive candidiasis where species of CANDIDA are present in the blood. "Three additional polymorphisms in CD58, LCE4A-C1orf68, and T-cell activation GTPase activating protein (TAGAP) loci associated with increased susceptibility to candidemia were identified in a genome-wide association study (GWAS) in the largest candidemia cohort to date." (PMID 29371502, 2018). "A significant association between candidemia and SNPs in cluster of differentiation (CD) 58 (odds ratio, OR = 4.68), late cornified envelope 4A (LCE4A; OR = 4.25) and T cell activation RHO-GTPase-activating protein (TAGAP; OR = 2.96) loci was identified." (PMID 28080988, 2016).
Autoimmunity (3 papers, 2020 to 2023). The occurrence of an immune reaction against the organism's own cells or tissues. "Some researchers have put forward that TAGAP variation modulates the risk of autoimmunity by altering thymocyte migration during thymic selection." (PMID 32337264, 2020). "Moreover, dectin-induced signaling was linked to the activation of an effective T helper cell immune response during antifungal host defense and autoimmunity, with TAGAP participation." (PMID 37744350, 2023). "In summary, we report that TAGAP plays an important role in linking Dectin-induced signaling to the promotion of effective T helper cell immune responses, during both anti-fungal host defense and autoimmunity." (PMID 32312989, 2020). "Here the authors identify TAGAP as a Dectin-1 and EphB2-binding protein mediating antifungal innate immune signaling and cytokine production, and demonstrate TAGAP in non-T cells promotes Th17 response in mouse models of infection and autoimmunity." (PMID 32312989, 2020).
Crohn disease (3 papers, 2019 to 2022). A gastrointestinal disorder characterized by chronic inflammation involving all layers of the intestinal wall, noncaseating granulomas affecting the intestinal wall and regional lymph nodes, and transmural fibrosis. "The TAGAP gene locus has been associated with several inflammatory diseases, including Crohn’s disease." (PMID 36704549, 2022).
colitis (2 papers, 2016 to 2022). Inflammation of the colon. "Together, these results indicated that the increased expression of proinflammatory genes, the accumulation of colitogenic CD4+ T cells, and the development of severe colitis in TAGAP-deficient mice is dependent on the microbiota." (PMID 36704549, 2022). "Cumulatively, these data suggested that the severe colitis phenotype seen in TAGAP deficiency is critically mediated by the gut microbiota, is transferable via FMT, and is associated with increased numbers of colitogenic CD4+ T cells." (PMID 36704549, 2022). "Here, we report that TAGAP-deficient mice are susceptible to DSS-induced colitis, and this is due to significantly increased abundance of IL-17A-and IFN-γ-producing colitogenic CD4+ T cells in the gut." (PMID 36704549, 2022). "Consistent with this, reg3g complement effectively attenuated colitis severity in TAGAP-deficient mice." (PMID 36704549, 2022). "So, it seems that there is a contradiction between the less abundance of A. muciniphila in the TAGAP-deficient mice and more severe phenotype of TAGAP-deficient mice in colitis model." (PMID 36704549, 2022). "We explored whether CD4+ T cells were important mediators of the severe colitis phenotype observed in TAGAP deficiency." (PMID 36704549, 2022). "We therefore wondered whether, conversely, the exacerbation of colitis severity seen in TAGAP deficiency might also be transferrable." (PMID 36704549, 2022). "We also provide evidence showing that the gut microbiota is responsible for the dysregulation of T helper cells in TAGAP-deficient mice, and fecal transplantation of gut microbiota from wild-type mice can reverse the severity of the colitis phenotype in TAGAP-deficient mice." (PMID 36704549, 2022). "Because we had found that the severe colitis phenotype in TAGAP deficiency is abolished following depletion of the microbiota, we wondered whether FMT might be sufficient to rescue the severe colitis phenotype." (PMID 36704549, 2022). "To investigate the role of TAGAP in the pathogenesis of IBD, we tested how genetic deletion of TAGAP impacts colitis severity in the DSS colitis model." (PMID 36704549, 2022). "Given that genetic deletion of TAGAP markedly exacerbated colitis severity in the DSS mouse model, we hypothesized that rs212388 might confer increased IBD risk by modulating TAGAP gene expression." (PMID 36704549, 2022). "We also demonstrated that inhibition of IL-12/IL-23-mediated signaling, using anti-p40 antibodies, was sufficient to attenuate colitis severity in TAGAP-deficient mice, suggesting that colitogenic CD4+ T cells critically mediate the severe colitis phenotype seen in TAGAP deficiency." (PMID 36704549, 2022). "Together, these data indicate that following mucosal injury, TAGAP deficiency was associated with increased IL-17A-producing and IFN-γ-producing CD4+ T cells infiltration and proinflammatory gene expression, which greatly exacerbated colitis severity." (PMID 36704549, 2022). "From the survival rate, we found that A. muciniphila accelerated the death rate of control mice, while did not promote the death for TAGAP-deficient mice, and this may be because of severe phenotype of TAGAP-deficient mice in the colitis model." (PMID 36704549, 2022).
inflammatory bowel disease (2 papers, 2021 to 2022). A spectrum of small and large bowel inflammatory diseases of unknown etiology. "Common variants of the T-cell activation Rho GTPase-activating protein (TAGAP) are associated with the susceptibility to human inflammatory bowel diseases (IBDs); however, the underlying mechanisms are still unknown." (PMID 36704549, 2022).
lung adenocarcinoma (2 papers, 2020 to 2023). A carcinoma that arises from the lung and is characterized by the presence of malignant glandular epithelial cells. "To validate the association between TAGAP and tumor-infiltrating lymphocytes, we analyzed publicly available single-cell RNA sequencing datasets of lung adenocarcinoma." (PMID 37744350, 2023). "The results demonstrated that overexpression of TAGAP significantly enhanced the cytotoxicity of CD4+ T cells against lung adenocarcinoma cells compared to the control group, with the highest cytotoxicity observed at the T:E ratio of 1:5." (PMID 37744350, 2023). "Our study presents novel insights into the critical role of TAGAP in Lung Adenocarcinoma (LUAD), emphasizing its prognostic potential, relationship with immune cell infiltration, influence on CD4+ T cell activity, and predictive value for immunotherapy responsiveness." (PMID 37744350, 2023). "This study aimed to investigate TAGAP’s expression and its potential impact on CD4+ T cell function and prognosis in lung adenocarcinoma (LUAD)." (PMID 37744350, 2023).
follicular lymphoma (1 paper, 2023). Follicular lymphoma is a form of non-Hodgkin lymphoma characterized by a proliferation of B cells whose nodular structure of follicular architecture is preserved. "Interestingly, we found that the most instrumental SNP in the mature T/NK cell lymphoma MR models corresponded to rs1738074, which maps in the vicinity of TAGAP, a locus that has been recently associated with hepatitis B virus-associated follicular lymphoma." (PMID 37108375, 2023).
fungal infection (1 paper, 2020). "Overall, these data indicate that TAGAP-deficient mice had defect in against fungal infection." (PMID 32312989, 2020).
hepatitis B virus (1 paper, 2019). "Six IA genes, APOB, IMPDH1, SEC61G, IQGAP2, TAGAP, and IGKV4-1, were dysregulated (differential expression, p < 0.05) in only tumor samples of drinkers without hepatitis B virus (HBV) infection as compared to pure normal samples (from nondrinkers)." (PMID 31480259, 2019).
hyperlipidemia (1 paper, 2025). "Stratification by disease status and hyperlipidemia revealed that MCL1, F13A1, TLR8, and TAGAP were significantly upregulated in patients with both AS and hyperlipidemia compared with healthy individuals without hyperlipidemia (p < 0.05)." (PMID 41583468, 2025).
lung carcinoma (1 paper, 2023). "In the current study, the results of analysis of lung cancer samples from the GEO single-cell dataset, RT-qPCR, and immunohistochemical analysis showed that T CD4+/CD8+ cell expression was correlated to TAGAP." (PMID 37744350, 2023).
viral infection (1 paper, 2022). "The 7-Mb QTL region on SSC1 and the 40-Mb QTL region on SSC10 only overlapped with enriched DE genes for bacterial or viral infection but harbors 2 immune related genes, IGF2R and TAGAP." (PMID 35100362, 2022).